PTH (parathyroid hormone)
Diseases named in the same sentence as PTH in open-access papers (continued):
Sharing a sentence is not in itself a finding about the gene and the disease.
Hypercalcemia (continued). "In these patients, a potential interaction exists between a xenospecific PTH-independent hypercalcemia and hypophosphatemia, and a recipient environment with persistently high PTH which has not been modeled in NHPs." (PMID 37311769, 2023). "In our previous research, we found that subcutaneous doses of 0.83 mg/kg and 8.3 mg/kg body weight did not trigger hypercalcemia, hypercalciuria, or reduction in parathyroid hormone levels throughout their examination period." (PMID 37760917, 2023). "Given the asymptomatic course, the absence of hypercalcemia symptoms, serum calcium, and PTH was not tested at the preoperative stage." (PMID 37183888, 2023). "On routine workup he was found to have hypercalcemia with a calcium level of 18 mg/dl [4.49 mmol/l, alkaline phosphatase 93 U/l, and parathyroid hormone (PTH) 69.1 pg/ml (10–65 pg/ml)] but serum phosphate was not checked." (PMID 37264371, 2023). "Laboratory tests generally show hypercalcemia (>13 mg/dL) and high levels of parathormone (PTH) (2–10 times above the normal range); <10% of cases are normocalcemic." (PMID 37834940, 2023). "Measurement of PTH pre- and post-transplant demonstrated appropriate suppression in the setting of hypercalcemia and no PTHrP was detected." (PMID 37311769, 2023). "Lehmann and Lee (2013) recommended monitoring calcium levels more frequently and observing for clinical symptoms in cases of mild asymptomatic hypercalcemia and absence of PTH level elevation while continuing lithium therapy." (PMID 36547749, 2022). "Disorders associated with calcium can be classified as hypocalcemia or hypercalcemia and they usually coexist with other serum biochemical abnormalities, including the levels of phosphate, alkaline phosphatase (ALP), PTH, fibroblast growth factor 23 and vitamin D." (PMID 36142318, 2022). "This increases the levels of calcium in the blood even in the absence of other etiologies of hypercalcemia in hematologic malignancies (i.e., ectopic production of PTH, high level of vitamin D, PTH‐rP production, or bone metastasis)." (PMID 35846936, 2022). "As the patient had no history of drug use to justify serum calcium levels and had not presented any state of prolonged immobilization, severe PTH-independent hypercalcemia was diagnosed." (PMID 36518777, 2022). "The basis of hypercalcaemia in these patients is uncertain, although elevated PGE2 may contribute as studies have shown it can stimulate bone resorption, increase PTH secretion and upregulate hydroxylation of 25-hydroxyvitamin D." (PMID 33990852, 2022). "Until now, all patients with multiple parathyroid lesions have normal levels of PTH and calcium and no symptoms of hypercalcemia." (PMID 36013465, 2022). "We reviewed his medical records from 2013, and the laboratory examination revealed hypercalcaemia as well as hypophosphatemia; however, PTH was not tested at that time." (PMID 35945539, 2022). "Parathyroid carcinoma (PC) is an extremely rare malignancy, accounting less than 1% of all parathyroid neoplasms, and an uncommon cause of primary hyperparathyroidism (PHPT), characterized by an excessive secretion of parathyroid hormone (PTH) and severe hypercalcemia." (PMID 35282432, 2022). "The diagnosis is usually made in children with hypercalcemia with elevated or non-adapted “normal” PTH levels; genetic screening is recommended, especially because of the risk of adenocarcinoma of the parathyroid with specific mutations as in the CDC73 gene." (PMID 36090548, 2022). "Clinically, FHH is a benign, typically asymptomatic disease and usually presents with the biochemical triad: life-long, non-progressive hypercalcemia, normal or slightly increased serum PTH levels and hypocalciuria." (PMID 35566721, 2022).
Hypercalcemia (continued). "Based on a narrative review of the effects of lithium on calcium and parathyroid hormone (PTH) homeostasis and its clinical implications, experts developed a step-by-step algorithm to guide the initial management of emergent hypercalcemia during lithium treatment." (PMID 36547749, 2022). "Approximately 2.0% of non-geriatric and 5.1% of geriatric lithium users have hypercalcemia and 23% of users have elevated PTH levels." (PMID 36153583, 2022). "Under medical treatment for hypercalcemia with denosumab and cinacalcet, the PTH level gradually increased, while serum calcium level did not change." (PMID 33858470, 2021). "It is easy to distinguish between PTH-dependent and non-PTH-dependent hypercalcemia in patients with acromegaly because in the latter, the hypercalcemia is accompanied by inhibition of PTH and is reversed with remission of the acromegaly." (PMID 33933067, 2021). "If hypercalcemia emerges, PTH measurement is warranted, but as stated, routine PTH monitoring (without hypercalcemia) is not recommended." (PMID 34863037, 2021). "Calcium based binders can be used as the initial binder therapy in CKD patients but are not the preferred option in case of hypercalcemia and/or when plasma PTH concentrations are < 150 pg/mL on two consecutive blood tests." (PMID 33895867, 2021). "It is caused by bone osteolysis due to metastases (20% of cases), paraneoplastic secretion of parathyroid hormone-related protein (PTHrP) (80%), configuring a humoral hypercalcaemia of malignancy (HHM), and rarely by ectopic parathyroid hormone (PTH) (<1%) or 1,25-dihydroxyvitamin D secretion (<1%)." (PMID 34093441, 2021). "Parathyroid carcinoma is typically characterized by significant hypercalcemia and high PTH levels, but there are no specific biochemical features that allow for differentiation from benign parathyroid lesions." (PMID 33839893, 2021). "For this reason, subtotal PTx seems indicated/appropriate in the presence of persistent hypercalcemia or -phosphatemia even without a defined PTH threshold and even more so when the patient is refractory to medical therapy." (PMID 33892650, 2021). "A 38-year-old female was diagnosed with PHPT at a non-university hospital, based on a modest hypercalcemia, and elevated PTH of 9.2 pmol/L and high to normal urinary calcium excretion of 8.5 g/L and calcium-to-creatinine clearance above 0.02." (PMID 33544354, 2021). "The diagnosis of PHPT in pregnancy can be confirmed in the presence of hypercalcemia (elevated serum ionized calcium or calcium adjusted for albumin) with a non-suppressed parathyroid hormone (PTH) level." (PMID 34209340, 2021). "The determination of parathyroid hormone (PTH) in cats could be of clinical utility in many metabolic disorders, such as renal diseases, hypercalcemia, or nutritional imbalances." (PMID 34827832, 2021). "In the present subjects, the mean concentrations of highly sensitive PTH and serum Ca were within normal ranges; thus, hyperparathyroidism and hypercalcemia were considered to be absent." (PMID 33728061, 2021). "Children present with non-specific signs of hypercalcemia (failure to thrive, vomiting, polyuria and polydipsia) with appropriately low parathormone (PTH) and inappropriately high 1,25-(OH)2D, suggesting deregulation of vitamin D metabolism." (PMID 34721296, 2021). "In contrast, once hypercalcemia was suppressed by diet, PTH administration no longer prevented EAE, suggesting that hypercalcemia prevented EAE after disease induction in female mice." (PMID 34046214, 2021). "Mild-to-moderate hypercalcemia with non-suppressed or high parathyroid hormone (PTH) levels present in patients with primary hyperparathyroidism (PHPT), typically." (PMID 34736428, 2021). "A systematic review/meta-analysis published in 2012 reports that most studies, usingcinacalcet for the treatment of pHPT and hypercalcemia, were not randomized, butshowed good control of Ca and PTH." (PMID 34910805, 2021).
Hypercalcemia (continued). "Hypercalcemia will lower 1,25-(OH)D and intact PTH levels secondary to a negative feedback mechanism." (PMID 33732556, 2021). "PTH regulates calcium metabolism (23, –25), mild hypercalcaemia was observed in 11% of patients in a clinical trial, and PTH should not be used in patients with hypercalcaemia." (PMID 34140410, 2021). "In these patients, hypercalcemia does not usually resolve after elimination of growth hormone (GH) excess, with serum PTH concentrations always being high or at the upper boundary of the normal range." (PMID 33933067, 2021). "Clinically, FHH1 is characterized by mild, non-progressive hypercalcemia, normal (in 80% of cases) or slightly elevated (in 20% of cases) serum PTH levels and hypocalciuria featured by low (<0.01) calcium-to-creatinine clearance ratio (CaCrCR)." (PMID 33528764, 2021). "Two dogs in this series developed hypercalcemia of malignancy, which was not confirmed by PTH-rp evaluation." (PMID 34944221, 2021). "FHH typically presents with the biochemical triad: life-long, non-symptomatic, non-progressive hypercalcemia, normal or slightly elevated serum PTH levels and hypocalciuria." (PMID 34659108, 2021). "Other effects of hypercalcemia include the activation of calcium-sensing receptors in the parathyroid gland that reduces PTH through negative feedback." (PMID 33732556, 2021). "During the course of chronic renal failure, SHPT can develop into THPT in which, presumably because of prolonged stimulation, the parathyroid gland proliferates, autonomously secretes PTH regardless of feedback and thereby leading to hypercalcemia." (PMID 33892650, 2021). "FHH is inherited in an autosomal dominant manner and usually results in mild hypercalcemia, non-suppressed or mildly elevated PTH, and relative hypocalciuria." (PMID 33716975, 2021). "Familial hypocalciuric hypercalcemia (FHH) should also be considered in the differential diagnosis of hypercalcemia along with a non-suppressed PTH." (PMID 34209340, 2021). "This strain of mice was then treated with PTH to induce hypercalcemia, without changing the circulating levels of 1,25-(OH)2D3." (PMID 34046214, 2021). "On the other hand, both 25‐(OH)2D3 and PTH levels were significantly decreased in patients with hypercalcemia compared with patients without hypercalcemia." (PMID 33145966, 2020). "PHPT is diagnosed in the presence of hypercalcemia and elevated or inappropriately normal (nonsuppressed) parathyroid hormone levels." (PMID 32555278, 2020). "In only one case, the main goal was hypercalcemia, in a setting of normal, but non-suppressed PTH level; this indication was combined with nausea and low tolerance to oral calcimimetics." (PMID 32075103, 2020). "Hypercalcemia inhibits PTH release via negative feedback; conversely, the suppressed PTH level reduces the calcium reabsorption by the renal tubule, and increases urinary calcium excretion." (PMID 32758178, 2020). "The presence of hypercalcemia at baseline or development of hypercalcemia during the study in any of the groups showed no connection to evolvement over time of PTH, calcidiol, creatinine, and eGFR." (PMID 32162241, 2020). "Nevertheless, it should be noted that in some cases substitution was not indicated due to either hypercalcaemia, hyperphosphataemia, or suppressed levels of PTH." (PMID 31218231, 2019). "Although measurement of the 1,25(OH)2D level is not mandatory in all cases of hypercalcemia, it is indicated in a patient who has low serum PTH levels." (PMID 31687644, 2019). "His PTH levels normalized and he did not require treatment for hypercalcemia, however, several months later, a new liver lesion was found, and this time a core biopsy revealed metastatic parathyroid carcinoma, which was not amenable to surgical excision." (PMID 31708875, 2019).
Hypercalcemia (continued). "Initial postnatal genetic testing adopted a targeted single gene approach to explore NSHPT; the initial working diagnosis supported by periosteal changes and marked PTH elevation, although absent hypercalcemia was contradictory." (PMID 30144375, 2018). "In many instances, the first sign of PHPT in a patient with MEN1 syndrome is hypercalcemia on routine laboratory work with concomitant non-suppressed (i.e., inappropriately normal) or elevated intact PTH levels in a patient <30 years old." (PMID 30459713, 2018). "Furthermore, the administration of parathyroid hormone (PTH) to osteoporosis patients induces adverse effects such as headache, nausea, cramps, and hypercalcemia." (PMID 30154383, 2018). "Hypercalcemia was more frequent in the groups with higher PTH and no pre-transplant PTX during follow-up." (PMID 29478201, 2018). "The hypercalcemia did not suppress, in this case, the production of 1,25 dihydroxyvitamin D through the suppression of PTH, as would happen in a normal physiologic response." (PMID 29673407, 2018). "No upper PTH limit for renal transplantation has been defined, but hypercalcemia is generally not accepted." (PMID 29478201, 2018). "Since the KDIGO CKD-MBD Guidelines were developed in 2009 two RCTs have demonstrated increased hypercalcemia without any clinically relevant benefit in PTH lowering compared to earlier studies included in the 2009 KDIGO Guidelines." (PMID 30236082, 2018). "In the hypercalcemias of malignancy, such elevations of parathyroid hormone are virtually never seen." (PMID 28900835, 2017). "It is difficult however to achieve a definitive diagnosis of this disease pre-operatively unless we keep this disease in mind, as it exhibits neither hypercalcemia nor PTH elevation." (PMID 28726134, 2017). "Our case was also discovered with hoarseness without hypercalcemia or high PTH value; it was difficult to make a diagnosis preoperatively." (PMID 28726134, 2017). "Five infants of our study group without dismorphic features displayed mild hypercalcemia, hypercalciuria, low serum PTH, normal serum 25OHD, and were diagnosed as IIH." (PMID 28443817, 2017). "Low PTH and hypercalcemia without hyperphosphatemia have been reported in horses and rabbits with renal failure and the decreased PTH has been attributed to the inhibitory effects of hypercalcemia." (PMID 27243456, 2016). "Whereas elevated parathormone (PTH) levels and hypercalcemia are significant features of PHPT, PTH elevation does not accompany hypercalcemia in secondary hyperparathyroidism (SHPT)." (PMID 26377856, 2016). "The patient without finding of abnormal glands and one of the patients that only got removed histologically normal glands showed postoperative pHPT with hypercalcaemia and not suppressed PTH." (PMID 25773486, 2016). "Today, in industrialized countries, non-calcium phosphate binders and higher serum PTH targets are used to prevent an excessive calcium load and hypercalcemia and, therefore, iatrogenic ABD is infrequently reported." (PMID 27756251, 2016). "Unfortunately due to limited finances the 1,25-dihydroxyvitamin D and parathyroid hormone were not assayed and these would have shed further light on the possible sources of hypercalcemia in our index patient." (PMID 26635987, 2015). "Hypercalcaemia associated with CAKUT in infancy is not all that uncommon and was reported in 15/99 infants in another study, most of whom had a suppressed PTH similar to that of our patient." (PMID 26019888, 2015). "One patient had a mild hypercalcemia (2 %, 2.71 mmol/l) and one a severe hypocalcemia (2 %, 1.63 mmol/l) with normal PTH levels and without typical symptoms." (PMID 26467771, 2015). "Our case report suggests that hypercalcaemia may result from the overproduction of PTHrP in patients with CAKUT and adequately suppressed PTH." (PMID 26019888, 2015).
Hypercalcemia (continued). "In patients with these conditions, in the early stages of the disease, there is a rise in PTH (or inappropriately normal PTH - not suppressed at the beginning of the hypercalcemia), which can confound the differential diagnosis." (PMID 26213611, 2015). "In these patients initial evaluation reveals increased or inappropriately normal PTH (not suppressed in the setting of hypercalcemia) which narrows the differential diagnosis." (PMID 24716007, 2014). "In the other 10 cases further neck exploration by a standard cervical approach was negative and in four of these persistent postoperative hypercalcemia was demonstrated, whereas in six patients postoperative normal calcemia and PTH were found." (PMID 24044556, 2013). "Our patient had a classical presentation of calcitriol-mediated hypercalcemia with hypercalciuria, elevated levels of serum calcitriol, and suppressed levels of PTH, accompanied by a negative workup for malignancy and sarcoidosis." (PMID 24363673, 2013). "Primary hyperparathyroidism is diagnosed when PTH is elevated, in the context of hypercalcemia, in a patient with no history of renal disease." (PMID 21747852, 2011). "Human studies show increase in BMD similar to that with PTH, but without significant hypercalcemia or other adverse effects as observed with PTH." (PMID 21209785, 2010). "In fact, in 11 cases, the PTH level has not been reported, and in one, hypercalcemia depended on simultaneous hypersecretion of PTH." (PMID 18291038, 2008). "In light of the reported data, PTHrP plays a critical role in defining the pathogenesis of atypical hypercalcemia due to parathyroid adenoma without hypersecretion of PTH." (PMID 18291038, 2008). "The activity of 1α-hydroxylase in the kidney is tightly regulated by PTH and 1,25(OH)2D3 and even large increases in serum 25(OH)D3 will not produce hypercalcemia." (PMID 16280049, 2005). "Transient reduction in serum calcium may occur shortly after initiation, yet no sustained effect on hypercalcemia or PTH levels is observed." (PMID 41210508, 2025). "However, AHO is typically associated with hormonal resistance, particularly parathyroid hormone (PTH) resistance, leading to hypercalcemia and hyperphosphatemia, which were not evident in our patient." (PMID 39834885, 2025). "Calcium homeostasis, which is tightly regulated by vitamin D, PTH, and calcitonin, remained stable, indicating that the doses of vitamin D were within a physiological range that supports normal calcium metabolism without inducing hypercalcemia." (PMID 40756379, 2025). "However, some scholars suggest that it can also be defined as persistent PTH elevation 6 months post–transplantation, with or without hypercalcemia." (PMID 41036144, 2025). "Initial clinical manifestations of patients with PTC combined with primary hyperparathyroidism (PHPT) can vary, with some being nonspecific, such as asymptomatic neck mass, hypercalcemia with or without symptoms, or fatigue, or even normal total serum calcium and PTH levels." (PMID 39054438, 2024). "The intake of vitamin D may result in toxicity, which manifests with hypercalcemia, hypercalciuria, low PTH, hyperphosphatemia, and not necessarily increased 1,25(OH)2D concentration." (PMID 38397979, 2024). "Notably, she had primary hyperparathyroidism (parathyroid hormone [PTH] 16.8 pmol/L [158.5 pg/mL], reference 1.6-6.9 pmol/L; [15.1-87.7 pg/mL]) and mild hypercalcemia (albumin-corrected calcium 2.76 mmol/L [11.06 mg/dL], reference 2.10-2.60 mmol/L; [8.4-9.5 mg/dL])." (PMID 39011405, 2024). "We present a case of severe hypercalcemia in a 53-year-old woman, initially suggestive of primary hyperparathyroidism due to non-suppressed intact parathyroid hormone (PTH) levels and unilateral intrathyroidal tracer uptake on a technetium 99m sestamibi parathyroid scan." (PMID 38623131, 2024).